CDC45 (cell division cycle 45)
Diseases named in the same sentence as CDC45 in open-access papers (continued):
Sharing a sentence is not in itself a finding about the gene and the disease.
epithelial dysplasia (4 papers, 2008 to 2024). "The expression of CDC45 increased in tongue squamous cell carcinomas, and its level was positively correlated with grades of precancerous lesions in epithelial dysplasia." (PMID 34257537, 2021). "The expression of Cdc45 increased in tongue squamous cell carcinomas and the level of Cdc45 was shown to have positive correlation with grades of precancerous lesions in epithelial dysplasia." (PMID 29651420, 2018). "CDC45 mRNA level was significant lower in mild epithelial dysplasia than in the moderate epithelial dysplasia, severe epithelial dysplasia, and SCC (p = 0.008, < 0.001, and 0.026, respectively; Mann-Whitney test)." (PMID 19116018, 2008). "The mRNA levels of CDC6, CDT1, MCM2 and CDC45 in 31 cases of precancerous epithelial dysplasia and 33 cases of squamous cell carcinoma of the tongue from formalin-fixed, paraffin-embedded specimens were measured using QRT-PCR." (PMID 19116018, 2008). "In this study, we found that CDC6, CDT1, MCM2 and CDC45 mRNA expression analyzed by quantitative real-time PCR are significantly higher in malignant SCC than mild precancerous epithelial dysplasia, and the expression levels in general increase with increasing grade of dysplasia." (PMID 19116018, 2008).
ovarian carcinoma (4 papers, 2014 to 2024). A malignant neoplasm originating from the surface ovarian epithelium. "The inclusion of CDC45 suggests the possibility that it is also associated with ovarian cancer." (PMID 31060502, 2019). "A recent study shows that CDC45 knockdown impaired DNA damage and induced resistance to combination therapy in ovarian cancer cells." (PMID 35810383, 2022).
prostate carcinoma (4 papers, 2020 to 2024). A carcinoma that arises from epithelial cells of the prostate gland. "In addition, CDC45 was only detected to be potentially correlated with prostate cancer based on co-expression network analysis and functional enrichment analysis, indicating that more empirical evidence was expected to validate the functions of CDC45 in prostate cancer." (PMID 35360870, 2022).
Fanconi anemia (3 papers, 2021 to 2025). Fanconi anemia (FA) is a hereditary DNA repair disorder characterized by progressive pancytopenia with bone marrow failure, variable congenital malformations and predisposition to develop hematological or solid tumors. "Subsequently, TARIP has been shown to ubiquitylate the replicative CMG (CDC45/MCM2–7/GINS) helicase, thereby regulating the NEIL3 pathway and Fanconi anemia pathway in the DNA interstrand crosslink repair process." (PMID 34349117, 2021).
gastric cancer (3 papers, 2022 to 2024). A primary or metastatic malignant neoplasm involving the stomach. "The ROC analysis further substantiated the reliability of CDC45 as a diagnostic marker for gastric cancer (GC), as evidenced by a robust area under the curve (AUC) exceeding 0.950." (PMID 38515458, 2024). "In this study, we employed the CIBERSORT method to examine the association between CDC45 expression and tumor-infiltrating immune cells in gastric cancer (GC)." (PMID 38515458, 2024). "Notably, the diagnostic potential of CDC45 was conducted rigorously evaluated in the TCGA cohort, wherein it exhibited a strong diagnostic capability to discriminate gastric cancer (GC) cases." (PMID 38515458, 2024). "Taken together, these findings provide compelling evidence supporting the potential of CDC45 as a predictive tumor biomarker for the diagnosis and prognosis of gastric cancer." (PMID 38515458, 2024). "One final leader gene for stomach cancer, CDC45, was identified from three subcellular location-specific networks and the disease network." (PMID 36226184, 2022). "Furthermore, although we found that CDC45 is excellent in the early diagnosis of gastric cancer, how it relates to atypical hyperplasia warrants further investigation." (PMID 38515458, 2024). "99, CDC45 is reportedly a crucial biomarker for gastric cancer as well." (PMID 37231064, 2023). "However, the clinical significance of CDC45 in gastric cancer (GC) remains unreported." (PMID 38515458, 2024). "In brief, our study suggests CDC45 upregulates in gastric cancer and provides crucial information for the diagnosis and prognosis for GC patients." (PMID 38515458, 2024). "It was observed that CDC45 expression was upregulated in different malignancies, particularly in gastric cancer (GC) where mRNA levels were significantly higher compared to both normal tissues and adjacent normal tissues." (PMID 38515458, 2024). "However, there are few studies on the role of CDC45 in gastric cancer." (PMID 38515458, 2024).
hepatocellular carcinoma (3 papers, 2021 to 2025). A malignant tumor that arises from hepatocytes. "IMP2 promotes glycolysis in hepatocellular carcinoma (HCC) by stabilizing CDC45 mRNA through m6A modification, which increases its expression." (PMID 40141058, 2025).
tongue squamous cell carcinoma (3 papers, 2008 to 2021). A squamous cell carcinoma that arises from the tongue. "Our results show that CDC45 mRNA is overexpressed in high grade dysplastic lesions and in tongue SCC." (PMID 19116018, 2008). "The nonparametric receiver operating characteristic analysis suggested that MCM2 and CDC45 had a higher accuracy than CDC6 and CDT1 for distinguishing dysplasia from tongue SCC." (PMID 19116018, 2008). "In other words, MCM2 and CDC45 had a higher accuracy than CDC6 and CDT1 for distinguishing precancerous stages from malignant tongue SCC." (PMID 19116018, 2008). "The area under the ROC curve (AUC) was 0.679 for CDC6 (p = 0.032), 0.808 for CDT1 (p = 0.000), 0.933 for MCM2 (p = 0.000) and 0.836 for CDC45 (p = 0.000), indicating that MCM2 and CDC45 were superior to CDC6 and CDT1, and could be used as useful tumor markers in diagnosing tongue SCC." (PMID 19116018, 2008).
acute myeloid leukemia (2 papers, 2022 to 2024). Acute myeloid leukemia (AML) is a group of neoplasms arising from precursor cells committed to the myeloid cell-line differentiation. "Recent studies have also shown that CDC45 regulated MCM7 in acute myeloid leukemia through the PI3K/AKT pathway, and another mechanism whereby replication partially disrupted eukaryotic DNA replication and triggered by ubiquitination of replication helicases." (PMID 36186452, 2022).
breast tumors (2 papers, 2017 to 2021). "Regarding to the clinical relevance of our results, low expression levels of βArr1 were inversely correlated with CDC45, BUB1, CCNB1, and CCNB2 genes compared to normal tissue samples while positively correlated with poorer prognosis in breast tumours." (PMID 33452359, 2021). "TCGA data analysis also indicates the clinical relevance of our results, the low expression levels of βArr1 are inversely correlated with CDC45, BUB1, CCNB1, and CCNB2 genes compared to normal tissue samples while positively correlated with poorer prognosis in breast tumours." (PMID 33452359, 2021). "RT-qPCR detection confirmed the relationship of ALDOA with CDC45 and CCNB2 in breast tumors." (PMID 28191039, 2017). "We further detect transcripts of ALDOA and several hub genes in breast tumors by RT-qPCR, and Pearson’s correlation analysis demonstrated a positive relationship of ALDOA with CCNB2 and CDC45, but not CDC20 and TK1, even a trend observed between them." (PMID 28191039, 2017).
colon cancer (2 papers, 2024). "This study revealed that remimazolam promoted the cell-cycle progression and proliferation of HCT8 colon cancer cells by upregulating CDK1, PTTG1, CDC25C, CDK4, PLK1, PCNA, Ki67, RNASEH2B, FEN1, Cyclin D1,CD44 CDK2, CDKN3, CDC45, IQGAP3, and CDK6." (PMID 38725628, 2024).
DiGeorge Syndrome (2 papers, 2022 to 2023). "Sequencing of a cohort of individuals with DiGeorge syndrome revealed several hemizygous variants in CDC45 in those with atypical features similar to the MGORS cohort described." (PMID 37059840, 2023). "CDC45 is located on chromosome 22, within the genomic region associated with DiGeorge syndrome (MIM 188400)." (PMID 37059840, 2023).
leukemia (2 papers, 2021 to 2023). A malignant (clonal) hematologic disorder, involving hematopoietic stem cells and characterized by the presence of primitive or atypical myeloid or lymphoid cells in the bone marrow and the blood. "CDC45 is upregulated in various human carcinomas, leukemia, and lymphoma." (PMID 37587140, 2023). "Studies have shown that CDC45 is a proliferation-associated antigen that may promote tumorigenesis and metastasis, and that CDC45 is overexpressed in several cancer-derived cell lines, including carcinoma-, sarcoma-, leukemia-, and lymphoma-derived cells." (PMID 33982750, 2021).
liver cancer (2 papers, 2021). An epithelial or non-epithelial malignant neoplasm that arises from the liver. "Although the research has some limitations, we are committed to provide some basis for the biological function of CDC45 in liver cancer." (PMID 33614286, 2021). "In addition to CCNB1, CDK1, CDC45, BUB1B, and CCNA2, we also identified five hub genes in Chinese liver cancer, namely AURKA, KIF11, TOP2A, TPX2, and HMMR, which play a crucial role in regulating the cell cycle." (PMID 34257537, 2021).
microcephaly (2 papers, 2019 to 2021). A congenital or acquired developmental disorder in which the circumference of the head is smaller than normal for the person's age and sex. "Additionally, the CDC45L, encoding the essential component of the DNA replisome, CDC45, is associated with a microcephaly phenotype in which CS of variable severity, ranging from unilateral or bilateral coronal synostosis to multiple suture involvement, has been found." (PMID 34356089, 2021). "Although it remains to be seen whether human Cdc45 has similar interactions with checkpoint kinases, it is intriguing that checkpoint mutations also cause human diseases, such as Seckel syndrome, that share overlapping features with MGS, including microcephaly." (PMID 30595439, 2019).
osteosarcoma (2 papers, 2021 to 2022). A usually aggressive malignant bone-forming mesenchymal neoplasm, predominantly affecting adolescents and young adults. "RFC4, CDK3, CDC45 and NCAPG were found to be associated with osteosarcoma for the first time in our analysis, and thus could be novel diagnostic/prognostic biomarkers or treatment targets." (PMID 34156352, 2021). "In the osteosarcoma dataset of TARGET database, although BAP1 expression was similar in osteosarcoma tissues from patients with different clinicopathologic characteristics, it was positively correlated with BRCA1, CDC6, and CDC45." (PMID 36003792, 2022).
cutaneous melanoma (1 paper, 2021). A primary melanoma arising from atypical melanocytes in the skin. "Our results revealed several novel biomarkers and biological pathways that participate in the pathogenesis of cutaneous melanoma, and demonstrated the diagnostic and prognostic value of CDC45, CENPF, DTL, FANCI, GINS2, HJURP, TPX2 and TRIP13." (PMID 33531976, 2021).
Gorlin syndrome (1 paper, 2024). "In cellular assays, the effects of motif-disruptive mutations were validated, including loss of a nuclear localisation signal in the cell division control protein CDC45 by a mutation associated with Meier-Gorlin syndrome." (PMID 39009827, 2024).
lymph node metastasis (1 paper, 2024). "The results showed that CDC45 and CDT1 were highly expressed in the lymph node metastasis group, while ALDH1A1 and ASAH1 were downregulated." (PMID 38589907, 2024).
Lynch syndrome (1 paper, 2013). An autosomal dominant hereditary neoplastic syndrome characterized by the development of colorectal carcinoma and a high risk of developing endometrial carcinoma, gastric carcinoma, ovarian carcinoma, renal pelvis carcinoma, and small intestinal carcinoma. "Lynch syndrome tumors showed up-regulation of 1129 genes, e.g. genes involved in G1/S transition (CCNE, CCNH, E2F2 and CDK2), DNA replication (CDC45, RPA1, RFC5, MCM4 and POLD3) and chromosomal organization and mitosis (CCNB2, MLF1IP, CASC5, KIF2C and PLK4), which is in line with previous findings." (PMID 23951239, 2013).
Nephroblastoma (1 paper, 2022). An embryonal neoplasm characterized by the presence of epithelial, mesenchymal, and blastema components. "In addition, the ARACNE analysis inferred an interaction between CDC45 and KCNQ1DN (SF 6), an lncRNA related to Wilms’ tumor or nephroblastoma, the most common pediatric renal cancer affecting children 3–5 years old." (PMID 35445848, 2022).
tumor (48 papers, 2008 to 2025). "In terms of tumor immune infiltration, CDC45 was significantly associated with B cell, CD8 + T cell, CD4 + T cell, neutrophil, dendritic and macrophage cell infiltration (all p < 0.001)." (PMID 37642814, 2024). "Given the significant role of the tumor immune microenvironment in GC tumorigenesis and metastasis, we conducted an analysis to assess the association between CDC45 expression levels and immune infiltration cells, as well as immune checkpoint related genes." (PMID 38515458, 2024). "Recently, CDC45 expression was identified to associate with tumorigenesis and was useful for tumour prognosis." (PMID 33614286, 2021). "Genes dysregulated according to tumour grade included CDC45 and RAD51AP1, which are both associated with the ALT pathway." (PMID 32899298, 2020). "In this paper, we found that CDC45 was associated with immune checkpoints, suggesting that through the regulation of particular immune checkpoint genes, CDC45 may regulate tumor immune patterns." (PMID 37642814, 2024). "We therefore investigated whether the CDC45 expression was associated with tumor-infiltration immune cells in CC." (PMID 34557356, 2021). "Therefore, we investigated whether CDC45 expression was associated with tumor-infiltrating immune cells in CC using CIBERSORT." (PMID 34557356, 2021). "In vivo xenograft models demonstrated that CDC45 depletion significantly reduces tumor growth, underscoring the critical role of the IMP2-CDC45 axis in driving HCC progression." (PMID 40141058, 2025). "In particular, metabolites facilitate the expression of the MCM/CDC45 complex in tumor cells, which contributes to their malignant growth and simultaneously induces the expression of metastasis-related genes." (PMID 40887473, 2025). "Compared to the control group, the tumor cell colonies formed after the CDC45 knockdown were smaller and the number of colonies decreased." (PMID 38589907, 2024). "In parallel, we used the TISCH dataset to further validate the expression of CDC45 in the tumor microenvironment of KIRC at the single-cell level." (PMID 37642814, 2024). "Regarding immunity, CDC45 exhibited correlations with the tumor microenvironment, immune cell infiltration, and immune checkpoints." (PMID 37642814, 2024). "This study identified CDC45 as a key gene potentially influencing tumor stemness and lymph node metastasis." (PMID 38589907, 2024). "Compared to the control group, the mice injected with CDC45-RNAi lentivirus showed smaller tumor sizes." (PMID 38589907, 2024). "As the study of CDC45 progresses, more and more researchers had explored the expression of CDC45 in tumor cells." (PMID 37642814, 2024). "CDC45 is even involved in the proliferation, invasion, tumor angiogenesis, and formation of drug resistance in tumor cells." (PMID 38589907, 2024). "A high level of expression of CDC45 was found in different types of tumor cells, and in the study of the mechanism, it was found that CDC45 mainly regulated the abnormal expression of cyclin through cell cycle, which caused tumorigenesis." (PMID 37642814, 2024). "In our study, we identified four key genes (ALDH1A1, ASAH1, CDT1, and CDC45) that affect tumor cell stemness and lymph node metastasis." (PMID 38589907, 2024). "The human CMG helicase (Cdc45-MCM-GINS) is a novel target for anti-cancer therapy due to tumor-specific weaknesses in CMG function induced by oncogenic changes and the need for CMG function during recovery from replicative stresses such as chemotherapy." (PMID 37609279, 2023). "Using the Cancer Genome Atlas, prominent overexpression of Cdc45 is discovered in papillary thyroid cancer tissue, which impacts tumor sizes and cancer stages." (PMID 36776764, 2023). "Myc is one crucial factor in regulating cell growth and tumorigenesis, overexpression of Myc enhances the Cdc45 DNA binding ability and replication fork stalling, which indicates Myc‐induced RS collaborates with Cdc45 in tumor development." (PMID 36776764, 2023).